CENPVL3 (centromere protein V like 3)
Synonyms: CENPVP3
Gene: Protein-coding gene on chromosome X (51,617,020 to 51,618,912, reverse strand). Ensembl gene ENSG00000224109.
Gene Ontology:
Molecular function: carbon-sulfur lyase activity
Homologues: Orthologues: chimpanzee CENPVL3 (99% identical), macaque CENPVL3 (96% identical), tropical clawed frog cenpv (39% identical), zebrafish cenpv (29% identical), Caenorhabditis elegans F25B4.8 (19% identical). Paralogues in human: CENPVL1 (96% identical), CENPVL2 (96% identical), CENPV (51% identical).